TERT (telomerase reverse transcriptase)
Diseases named in the same sentence as TERT in open-access papers (continued):
Sharing a sentence is not in itself a finding about the gene and the disease.
thyroid cancer (continued). "The limitation of the current study may be that we failed to prove the clinical utility of BRAF, KRAS, NRAS, and TERT promoter mutation as circulating markers in early-staged thyroid cancers distinguishing from benign thyroid lesions or healthy individuals." (PMID 33915745, 2021). "In this study we tested whether BRAF and/or TERT promoter mutations conferred sensitivity to YK-4-279 in thyroid cancer cells and whether this inhibitor could be served as a therapeutic agent for advanced thyroid cancers." (PMID 34221969, 2021). "According to the results of previous studies, although the incidence of TERT promoter mutation is reported to be low, it may be worthwhile to test TERT promoter mutation in thyroid cancer patients because they are associated with a poor clinical prognosis." (PMID 34070093, 2021). "Thus, TERT promoter mutation-induced TERT can exert oncogenic functions via both telomere-dependent and telomere-independent mechanisms, thereby promoting the development and progression of thyroid cancer." (PMID 33669363, 2021). "Therefore, our results raise the question about the clinical utility of BRAF, KRAS, NRAS, and TERT promoter mutation analysis using ctDNAs of patients with thyroid cancers." (PMID 33915745, 2021). "In addition, the frequency of TERT promoter mutations is associated with aggressive characteristics of thyroid cancers." (PMID 33995657, 2021). "TERT promoter gain-of-function mutation is particularly important in thyroid cancer pathogenesis." (PMID 33669363, 2021). "In this study we aimed to investigate whether TERT promoter mutations confer sensitivity to ETS inhibitor YK-4-279 in thyroid cancer cells and whether this inhibitor could be served as a potential therapeutic agent for thyroid cancer." (PMID 34221969, 2021). "This study aimed to determine if TERT mutations could be independent predictors of thyroid cancer-specific mortality based on the AJCC TNM 8th edition, with long-term follow-up." (PMID 33562809, 2021). "A propensity of thyroid cancer cells to accumulate TERT promoter mutations, as additional molecular events other than early genomic drivers, is also supported by in vitro data reporting a very high frequency in papillary and follicular thyroid carcinoma-derived cell lines." (PMID 33543394, 2021). "Research shows that ETV4 is associated with tumor progression in several cancer types; in thyroid cancer, it may bind to the mutated TERT promoter, therefore increasing TERT expression." (PMID 32982961, 2020). "Additionally, the study of chromosomal architecture surrounding TERT, and the effect of the TERT mutation on 3D chromatin structure in thyroid cancer have yet to be explored." (PMID 32849278, 2020). "However, thyroid cancer with dual mutations of RAS with BRAF V600E or TERT was associated with worse clinicopathologic outcomes." (PMID 32393293, 2020). "Taken together, the additional molecular testing of BRAF, NRAS, and TERT promoter mutations not only enabled the identification of thyroid malignancies in FNAB cytology but also allowed the prediction of the aggressive characteristics of thyroid cancer." (PMID 33247684, 2020). "Indeed, two TERT regulatory mechanisms, TERT promoter mutations and TERT promoter methylation status, are implicated in the stratification of thyroid cancer patient prognosis." (PMID 32849278, 2020). "In addition, mutations within the telomerase reverse transcriptase (TERT) promoter region have been detected more frequently in aggressive thyroid cancer cases." (PMID 33158279, 2020). "In the new American Association of Endocrine Surgeons Guidelines for the Definitive Surgical Management of Thyroid Disease in Adults, there is acknowledgment of inclusion of the TERT promoter mutation in assessment of the overall mutational burden in thyroid cancers." (PMID 32849278, 2020).
thyroid cancer (continued). "Additional biomarkers including NRAS and TERT promoter mutations are acknowledged to have a potential clinical significance in thyroid cancer and could be applied in synergy with BRAF mutation." (PMID 33247684, 2020). "The presence of TERT promoter (TERTp) mutations in thyroid cancer have been associated with worse prognosis features, whereas the extent and meaning of the expression and activation of TERT in thyroid tumours is still largely unknown." (PMID 32659948, 2020). "Also, in thyroid cancer, TERT induction has been linked to a poorer prognosis, higher risk of metastases, recurrence, and even death." (PMID 32560331, 2020). "However, in terms of diagnostic utility, BRAF, NRAS, and TERT promoter mutations have shown greater potential due to the high prevalence and clinical features in thyroid cancer." (PMID 33247684, 2020). "Increased TERT gene copy number was associated with upregulation of the gene expression and correlated with worse clinical outcomes in breast, lung adenocarcinoma, Merkel cell carcinoma, and thyroid carcinoma." (PMID 32121056, 2020). "Indeed, coexistence of BRAF V600E and TERT promoter mutations was shown to be associated with increased expression of TERT in thyroid cancer." (PMID 31810221, 2019). "Previous studies have demonstrated that rs10069690 (C>T) polymorphism in the TERT is associated with susceptibility to multiple types of cancer, such as breast cancer, ovarian cancer, lung cancer, and thyroid cancer." (PMID 31454181, 2019). "Although further studies are needed, these outcomes indicate that TERT is a new oncogene in thyroid cancer and promoter mutations may be promising in clinical management of thyroid cancer, especially in combination with BRAF V600E or RAS mutations." (PMID 31717449, 2019). "The aim of this study was to detect novel mechanisms of TERT activation in thyroid cancer by mutational screening of the extended promoter region of TERT and evaluating copy number variations (CNVs) involving the TERT chromosomal locus in different thyroid cancers." (PMID 31408918, 2019). "This meta‐analysis suggested that the TERT rs10069690 polymorphism may be a risk factor for cancer, especially breast cancer, ovarian cancer, lung cancer, thyroid cancer, and RCC." (PMID 31454181, 2019). "Furthermore, promoter mutation of TERT has been identified to be significantly correlated with aggressiveness and recurrence in thyroid cancer in our previous studies." (PMID 31024447, 2019). "BRAF and TERT mutations have been extensively related to prognosis in thyroid cancer." (PMID 30884810, 2019). "These mutations, as well as TERT copy number alterations, may represent an additional mechanism of TERT activation in thyroid cancer." (PMID 31408918, 2019). "Interestingly, BRAF V600E was widely found to be associated with TERT promoter mutations in human cancers, particularly thyroid cancer and melanoma." (PMID 29422527, 2018). "In addition, some studies suggest TERT promoter mutations are among the earliest genetic events in bladder cancer, thyroid carcinoma, cutaneous melanoma, basal cell and squamous cell carcinoma and oligodendroglioma." (PMID 29463038, 2018). "We only found TERT promoter mutations in follicular-derived thyroid cancer with a follicular growth pattern—4/7 cases were widely invasive FTC (FTC-WI), and 3/7 were follicular variant of PTC (FV-PTC)—while none of the classical PTC in our series revealed any TERT mutations." (PMID 29085338, 2017). "Our results indicated that TERT promoter mutation, as a potential marker of aggressive behavior in thyroid cancers, might also partially account for the relatively aggressive biological behavior of HVPTC." (PMID 28423545, 2017). "A significant proportion of thyroid cancers harbour oncogenic mutations with the TERT promoter." (PMID 27852061, 2016). "Thus, this is currently an important unresolved issue on the role of TERT promoter mutations in thyroid cancer." (PMID 26943032, 2016).
thyroid cancer (continued). "Although both lncRNA dysregulation and TERT promoter mutations are significant features in thyroid cancer biology and telomerase dysregulation, the studies cited herein do not provide evidence that directly associates changes in lncRNA with TERT promoter mutations in thyroid cancer." (PMID 41154428, 2025). "TERT promoter mutations have been shown in 95% of thyroid tumors that have transformed from papillary carcinoma to a more aggressive anaplastic thyroid carcinoma and so pose a greater risk of transformation to a more aggressive and rare thyroid cancer compared to other mutations." (PMID 38539437, 2024). "However, TERT promoter mutations occur infrequently in thyroid cancer." (PMID 36984536, 2023). "Why some thyroid cancers with TERT promoter mutations tend to be more aggressive remains unclear." (PMID 36672362, 2023). "Thus, collecting a large number of thyroid cancer cases with TERT promoter mutations was difficult." (PMID 36984536, 2023). "However, most previous studies did not account for the presence of other rare mutations that may also influence the disease outcomes of thyroid cancer with TERT promoter mutations." (PMID 36672362, 2023). "However, the reason why some thyroid cancers with TERT promoter mutations are more aggressive than others remains unclear." (PMID 36672362, 2023). "In this study, the expression of Caspase-3 and Caspase-9 in miR- 195 mimic + TERT group cells was significantly increased, which may indicate that over-expressedmiR-195-5p mimics effectively increased apoptotic factors, causing thyroid cancer cells to be rapidly inhibited." (PMID 34482792, 2021). "Furthermore, the TERT promoter mutations are found in almost all thyroid cancer cell lines, even those derived from well-differentiated thyroid cancer (DTC) subtypes, in either the heterozygous or homozygous mutant state, indicative of their important role in cellular proliferation." (PMID 32849278, 2020). "Therefore, we postulated that TERT promoter mutation may have an important role in preoperative diagnosis of thyroid carcinoma, especially for patients with indeterminate cytology on FNAB." (PMID 31655978, 2020). "In addition to the diagnostic potential of TERT promoter mutations in urological and thyroid cancer, they may serve as useful biomarkers in other malignancies." (PMID 27438857, 2016). "For comparison with PTCs, PDCs, and ATCs, 13 thyroid cancer cell lines, derived from pTs with different degrees of differentiation or originated in DMs or LNMs of thyroid tumors, were evaluated for TERT amplification." (PMID 40272676, 2025). "The co-occurrence of TERT promoter mutations and BRAF-like mutations indicates an extremely high risk of thyroid cancer and is associated with increased extrathyroidal spread and lymph node metastasis risk." (PMID 40805132, 2025).
thyroid cancer (continued). "Similar to other malignancies, the emergence and advancement of thyroid cancer are accompanied by genetic mutations, such as RAS, BRAF, or TERT mutations, as well as RET and NTRK rearrangements." (PMID 40586006, 2025). "The prevalence of TERT promoter mutations increases progressively from well-differentiated thyroid cancers to ATC, with over 70% of ATCs harboring TERT promoter mutations." (PMID 40363930, 2025). "Of note, TERT promoter mutations are believed to be less frequent and subclonal in PTC compared with other subtypes of thyroid cancer." (PMID 40940966, 2025). "While still not fully understood, the activity of TERT in thyroid cancer is thought to both allow malignant thyrocytes to escape replicative senescence and contribute to cancer aggressiveness through extra-telomeric functions." (PMID 40396891, 2025). "These regulatory activities can lead to an increased abundance of TERT, which leads to increased telomerase activity in thyroid cancer cells, allowing cancer cells to avoid senescence and lapse into replicative immortality." (PMID 41154428, 2025). "Few studies have analyzed the prevalence of TERT amplification in thyroid cancer, showing discrepancies in various topics." (PMID 40272676, 2025). "Similar studies in thyroid cancer cell lines are needed to determine if the GABP tetramer is also an essential regulator of TERT amplification, mimicking TPM in activation strength and mechanism." (PMID 40272676, 2025). "Recent studies indicate that TERT promoter mutations are a prominent mechanism of telomerase activation in thyroid cancer, correlating with enhanced TERT expression and increased aggressiveness." (PMID 41154428, 2025). "Molecular profiling using our custom thyroid cancer gene panel revealed the molecular characteristics of this tumor, which showed additional mutations (KRAS and TERT‐p) in In‐N, indicating STc with malignant potential from the well‐differentiated Out‐N." (PMID 41090246, 2025). "Beyond the two most common TPM, which selectively recruit the ETS transcription factor GABP to activate TERT, the mechanism of telomerase reactivation in case of TERT amplification in thyroid cancer is poorly characterized." (PMID 40272676, 2025). "Future studies should include prospective analyses of thyroid cancer management changes related to TERT-positive thyroid nodules and cancer to see if a more aggressive initial approach to therapy improves thyroid tumor morbidity and mortality." (PMID 38441247, 2024).
thyroid cancer (continued). "The telomerase reverse transcriptase (TERT) is overexpressed and associated with poor prognosis in papillary thyroid cancer (PTC), the most common subtype of thyroid cancer." (PMID 38313800, 2024). "Then we analyzed the potential effect of TERT methylation on TERT expression by comparing the TERT mRNA levels in TERT hypomethylated and hypermethylated thyroid cancer samples." (PMID 38313800, 2024). "Two hotspot mutations, occurred collectively in around 10% of PTC, in the core promoter region of TERT activates the expression of TERT at the transcription level and thus promotes the tumorigenesis and development of thyroid cancer." (PMID 38313800, 2024). "Research indicates that TERT mutation is infrequent in children and teenagers, while combined with BRAF mutation, they contribute to increased malignancy in thyroid cancer." (PMID 38607456, 2024). "In thyroid cancer, TERT reactivation appears to be a late event in tumorigenesis, primarily the result of activating pTERTmut and clinically associated with more aggressive disease." (PMID 39717106, 2024). "Increased telomerase activity, as can occur with TERT promoter mutations, can maintain telomere length and induce cell immortality, which may mechanistically explain the generally more aggressive clinicopathologic features associated with TERT promoter mutated thyroid carcinomas." (PMID 38441247, 2024). "In papillary thyroid cancers the ETS variant 5 (ETV5) is abundantly expressed and able to activate mutant TERT promoter in GABP-negative thyroid cancer cells." (PMID 38033865, 2023). "The 13 thyroid cancer cases with a mutant TERT promoter comprised 5 conventional papillary thyroid carcinomas, 3 follicular thyroid carcinomas, 1 poorly differentiated thyroid carcinoma, and 3 anaplastic thyroid carcinomas." (PMID 36984536, 2023). "The number of somatic mutations, TERT promoter mutations, and the clonal architecture of BRAF mutations should be considered in the risk stratification of thyroid cancer." (PMID 37465126, 2023). "The 12 thyroid cancer cases with a wild-type TERT promoter comprised 8 conventional papillary thyroid carcinomas, 2 follicular thyroid carcinomas, and 2 poorly differentiated thyroid carcinomas." (PMID 36984536, 2023). "A comparison of the adjusted hazard ratio (HR) of age at diagnosis in the wild-type TERT (WT-TERT) and mutant TERT (M-TERT) groups of differentiated thyroid cancer (DTC)." (PMID 37948420, 2023). "Recent meta-analyses have revealed that thyroid cancers with concurrent BRAF V600E or RAS and TERT promoter mutations were associated with increased tumor aggressiveness compared to those harboring BRAF V600E, RAS, or TERT promoter mutations alone." (PMID 36672362, 2023). "TERT and BRAFV600E mutations, extrathyroidal extensions and high-grade histopathological thyroid cancer subtypes were associated with increased risk of development of RAIR." (PMID 37859987, 2023). "We also observed that TPMs likely render thyroid cancer cells less dependent to MAPK-mediated control of TERT transcription, whereas pharmacological inhibition of MAPK signaling effectively suppressed TERT mRNA levels in the absence of TPMs." (PMID 35053525, 2022). "Initially, four thyroid cancer cell lines were employed: TCO1, SW1736, and C643, which all harbor TERT c.-124C>T mutation, and Cal62, which was used as a control for a wild-type TERT promoter." (PMID 35053525, 2022).